TERT (telomerase reverse transcriptase)
Diseases named in the same sentence as TERT in open-access papers (continued):
Sharing a sentence is not in itself a finding about the gene and the disease.
thyroid cancer (continued). "A strong inducer of GABPB expression is FOS and T-5224, which is a new small molecule inhibitor of FOS, selectively suppress TERT expression in thyroid cancer cells carrying TERT promoter mutations but not in wild-type TERT cells." (PMID 38033865, 2023). "This study further emphasized the importance of TERT promoter mutation as an essential nonanatomical prognostic factor in thyroid cancer." (PMID 37948420, 2023). "First, analysis of other co-mutations and sub-analysis of specific co-mutations was not possible in our study because of the rarity of TERT promoter mutations, with its prevalence reported to be between 4.2% and 25% in well-differentiated thyroid cancer." (PMID 36672362, 2023). "BRAF, TERT and RAS gene mutations were frequently observed in thyroid cancer." (PMID 37745716, 2023). "A meta-analysis study including 173 TERT promoter mutant and 1587 TERT promoter wild-type thyroid carcinoma patients showed that the LNM probability ratios were 53.18% and 37.30%, respectively, and a significant association existed between TERT promoter mutation and LNM." (PMID 36817603, 2023). "With the dramatic development of molecular diagnostic technologies in recent years, researchers have discovered BRAF, RAS, and telomerase reverse transcriptase (TERT) promoter mutations, RET/PTC rearrangement, and other genetic mutations to be associated with thyroid cancers." (PMID 36133306, 2022). "first reported a link between mutations of the TERT promoter and BRAF (V600E) in PTC, and subsequent studies further demonstrated the coexistence of TERT promoter and BRAF(V600E) mutations in thyroid cancers and their association with the most aggressive PTC clinical factors and worse prognosis." (PMID 36004350, 2022). "Taken together, these data caution against GABPA being a universal regulator of the mutant TERT promoter in thyroid cancer cells and suggest that targeting GABPA over a sustained period is unlikely to result in a consistent reduction in TERT expression in this tumor type." (PMID 35053525, 2022). "Thus far, most thyroid cancer studies aimed at identifying mechanistic underpinnings of TERT mutant control have either focused on single ETS factors in several cell lines or screened multiple factors in a limited number of lines." (PMID 35053525, 2022). "The anti-tumor activity of YK-4-279 in thyroid cancer is independent of TERT promoter mutations and likely to be explained by inhibiting the expression of TERT and several DNA helicase genes." (PMID 34221969, 2021). "Mutations involving BRAF and TERT are important predictors of disease severity in thyroid cancer, but molecular testing is limited by cost and lack of adequate tissue sample." (PMID 34702207, 2021). "Therefore, in this study, we proposed a new prognostic staging system, TNM-8T, by incorporating the TERT promoter mutational status into the AJCC staging system, the most commonly recommended staging system for predicting the prognosis of thyroid cancer." (PMID 34208345, 2021). "Therefore, in addition to regulating DNA helicase expression, the anti-tumor activity of YK-4-279 can be explained partially by suppressing the oncogenic effect of TERT in thyroid cancer." (PMID 34221969, 2021). "The methodology could be of potential value for clinical screening purposes and might imply unconventional roles for nuclear TERT mRNA in thyroid cancer development." (PMID 34011619, 2021). "Given the frequency of its mutations in metastatic cancers, and their prognostic role in thyroid cancer, the TERT promoter could be a future therapeutic target." (PMID 33790328, 2021).
thyroid cancer (continued). "TERT C228T is far more prevalent than C250T in thyroid cancer." (PMID 34208345, 2021). "The observed down-regulation of hsa-miR-195-5p should be of particular interest for future studies, as this miRNA could constitute a potent tumor suppressor in thyroid cancer cell lines by targeting TERT mRNA." (PMID 34676499, 2021). "Since TERT is a master regulator in human cancer and plays vital roles in thyroid cancer, we hypothesized that the effect of YK-4-279 on thyroid cancer viability may be mediated, at least partially, by regulating TERT expression." (PMID 34221969, 2021). "Characterization of TERT promoter methylation as well as ETS transcriptional activator binding in specific thyroid cancer subtypes, especially in PDTC and ATC, may lead to potential treatment options for these fatal diseases." (PMID 32849278, 2020). "The 2015 American Thyroid Association Management Guidelines for Adult Patients with Thyroid Nodules and Differentiated Thyroid Cancer listed TERT, alone or in combination with BRAF, as potentially helpful to risk stratify patients in conjunction with other clinicopathological risk factors." (PMID 32849278, 2020). "TERT mRNA has been known as a promising prognostic marker in thyroid cancer." (PMID 32466217, 2020). "In another study, the integrative analysis of aggressive thyroid carcinomas, including ATC and advanced DTC, revealed the frequent presence of TERT, AKT1, PIK3CA, and EIF1AX mutations in combination with BRAFV600E and RAS mutations in these advanced forms of thyroid cancers." (PMID 32751138, 2020). "Thus, our results demonstrate that FOXD2-AS1 functions as a ceRNA sponge to disrupt the inhibitory effect of miR-7-5p on TERT, finally upregulating TERT expression in thyroid cancer cells." (PMID 31024447, 2019). "Silencing of miR-7-5p increased TERT expression in thyroid cancer cells." (PMID 31835496, 2019). "In addition, FOXD2-AS1 acted as an endogenous sponge or decoy for miR-7-5p, which further relieved the inhibitory effects of miR-7-5p on TERT, leading to the recurrence of thyroid cancer patients." (PMID 31024447, 2019). "Therefore, we posited that FOXD2-AS1 promotes the recurrence of thyroid cancer via regulating TERT expression." (PMID 31024447, 2019). "Importantly, inhibition of miR-7-5p increased the TERT expression in FOXD2-AS1-silenced thyroid cancer cells." (PMID 31024447, 2019). "In order to test whether CNV may represent another mechanism of TERT activation in thyroid cancer, DNA samples from 184 thyroid tumors were screened for CNV using a TaqMan copy number assay based on quantitative real‐time PCR (qPCR)." (PMID 31408918, 2019). "As expected, TERT expression was repressed by downregulation of FOXD2-AS1 in thyroid cancer cells." (PMID 31024447, 2019). "In summary, we report herein two novel TERT promoter alterations in thyroid tumors and show that these mutations are functional and lead to increase in the transcriptional activity of TERT promoter in thyroid cancer cells by creating new consensus motifs for transcriptional regulators." (PMID 31408918, 2019).
thyroid cancer (continued). "Moreover, in thyroid carcinoma TERT inhibition has been related to reduced cell growth, invasion, migration and angiogenesis." (PMID 30934988, 2019). "TERT promoter mutation, another potential marker of aggressive behavior in thyroid cancers, was also observed in HVPTC but not in CPTC, and was concurrent with BRAF V600E mutation." (PMID 28423545, 2017). "Somatic mutations of the promoter region of the TERT gene have been reported in various cancers, including thyroid cancers, but are not found in normal cells." (PMID 26857243, 2016). "Finally, with respect to the association between variants in/near FOXE1 and mechanisms of thyroid cancer risk, our data provides a new mechanism by which FOXE1 can affect cancer development via TERT upregulation." (PMID 27852061, 2016). "However, little is known about the impact of TERT promoter mutations and ALK rearrangement in thyroid cancer patients with a high prevalence of BRAF mutations." (PMID 26857243, 2016). "It has to be pointed out, however, that the prevalence of TERT promoter mutations is not high (10%–20%) in differentiated thyroid cancer, and the exclusion of malignancy should not be only based on undetectable TERT promoter mutations." (PMID 27438857, 2016). "TERT promoter mutations were not present in 192 well-differentiated thyroid carcinomas (WDTC) without distant metastasis or in 9 medullary carcinomas." (PMID 26857243, 2016). "The tumors with TERT promoter mutations in accordance with earlier observations in thyroid cancer had shorter telomeres than tumors without the mutations." (PMID 25797251, 2015). "Moreover, mutations in the telomerase gene (TERT) are frequently seen in aggressive thyroid cancers, including in poorly differentiated and anaplastic thyroid cancers, and lead to increased transcriptional activity of TERT." (PMID 25202329, 2014). "It appears that the two events might cooperate in TERT reactivation and thyroid cancer progression." (PMID 40272676, 2025). "Furthermore, lncRNAs may also influence TERT promoter methylation, histone modifications, and alternative splicing, adding another layer of control to telomerase functions in thyroid cancer cells." (PMID 41154428, 2025). "Hence, thyroid cancers designated as having wild-type promoters in the present study might have exhibited abnormal TERT functioning, although the possibility is quite small." (PMID 36984536, 2023). "Many fundamental mutations in thyroid cancer target different constituents of the MAPK signaling pathway, including BRAF V600E and RAS gene point mutations, RET::PTC and PAX8::PPARγ chromosomal rearrangements, and telomerase reverse transcriptase (TERT) promoter mutations." (PMID 36672362, 2023). "Moreover, in some cases of advanced thyroid cancer, PD-L1 might be co-expressed with BRAFV600E and TERT promoter mutations, information that might have important consequences on patient prognosis and the possibility of using target therapies." (PMID 37627081, 2023). "This is another reason to support the hypothesis that patients with thyroid cancer positive for TERT promoter mutations may not have aggressive disease." (PMID 36672362, 2023). "Integration analysis of telomere lengths with TERT promoter alterations and subtelomeric gene expression patterns prompted us to explore the chromatin organization of 5p subtelomeric region in tumours, leading to propose a new prognostic marker for thyroid cancer." (PMID 35979662, 2022).
thyroid cancer (continued). "In thyroid carcinomas, MYC overexpression develops by various means, including MYC amplification or rearrangements, BRAFv600e mutation interactions, specific long noncoding RNA dysregulation, increased BRD4 protein production, and abnormal TERT expression, among others." (PMID 34997561, 2022). "Other altered genes, such as TERT, a ribonucleoprotein polymerase that maintains telomere ends, have been described in all the histological thyroid cancer types, with a significantly higher prevalence in aggressive and undifferentiated tumors, indicating their role in thyroid cancer progression." (PMID 33572167, 2021). "Numerous studies have demonstrated that TERT promoter mutations, especially when accompanied with BRAF V600E or RAS mutations, showed strong correlation to aggressive clinical characteristics, radioiodine refractory and poor clinical outcomes in patients with thyroid cancer." (PMID 34221969, 2021). "Therefore, this study focused on the relationship between miRNA-195-5p and TERT in thyroid cancer." (PMID 34482792, 2021). "For thyroid gland cancer prediction, thyroglobulin antibody in serum or plasma by immunoassay (2.69%), thyroglobulin in serum or plasma (0.58%), T4 (thyroxine) (0.62%), and gene telomerase reverse transcriptase (TERT) (SHAP value 0.59%) were found to be the major contributors." (PMID 34032581, 2021). "In thyroid cancer, phosphorylation and activation of ETS factor ELK1 by BRAF/MAPK pathway were necessary for thyroid-specific FOXE1 recruitment to TERT promoter via direct ELK1–FOXE1 interaction and this recruitment was independent from cis-acting mutations of TERT promoter." (PMID 34221969, 2021). "Thus, it is likely to the case that the interaction between ETS and certain transcription activators, such as FOXE1, play an important role in TERT activation in thyroid cancer cells while YK-4-279 inhibits TERT expression by disrupting ETS factors’ interaction." (PMID 34221969, 2021). "Therefore, based on the results of our analysis, we suggest that it is helpful to identify candidate thyroid cancer patients with a poor prognosis to selectively perform the TERT gene mutation test in more advanced patients rather than in all patients." (PMID 34070093, 2021). "Finally, the clinical significance of TERT in thyroid cancer is also reviewed." (PMID 32849278, 2020). "In conclusion, we report that TERT expression may be correlated with worse prognosis features in malignant thyroid tumours but its expression in benign thyroid tumours should be carefully considered and analysed, particularly in the presence of lymphocytic infiltrate." (PMID 32659948, 2020). "Thus, novel functional mutations uncovered in this study and increased copy number of TERT may represent additional mechanisms of TERT activation in thyroid cancer." (PMID 31408918, 2019). "Interestingly, no occurrences of the BRAF mutation occurred alongside a TERT promoter mutation, suggesting a relative rarity of this mutation in comparison to its frequency in more aggressive thyroid cancers." (PMID 31443155, 2019). "Furthermore, mechanistic investigations revealed that FOXD2-AS1 functioned as a ceRNA by sponging miR-7-5p, which further upregulated telomerase reverse transcriptase (TERT) expression in thyroid cancer cells, finally contributing to the early recurrence of thyroid cancer." (PMID 31024447, 2019). "Since a variety of mechanisms are involved in TERT re-expression and telomerase activation, testing only of TPM has a limited prognostic value in advanced thyroid cancers." (PMID 40272676, 2025). "For comparison with PTC cases, the prevalence of TERT amplification and/or TPM was also evaluated in 50 aggressive thyroid cancers exhibiting a PDC (15 cases) or an ATC (35 cases) phenotype." (PMID 40272676, 2025).
thyroid cancer (continued). "However, testing all thyroid cancers for the TERT promoter mutation might not be cost effective considering the low incidence of TERT promoter mutations in thyroid cancer." (PMID 36984536, 2023). "The combination of TERT and BRAFV600E had a sensitivity of 38.0% and specificity of 100% for thyroid cancer." (PMID 34702207, 2021). "The present study showed that overexpression of miR-195-5p inhibits TERT, which significantly reduces the presence of Ki67 and PCNA in thyroid cancer cells CAL-62, and inhibits the proliferation of CAL-62." (PMID 34482792, 2021). "Based on previous reports, there are currently several biomarkers that have clinical implications for thyroid cancer including RET/PTC, RAS, BRAF, PAX8-PPARγ, MicroRNAs (miR-221, 222, and 181b), and activation of telomerase reverse transcriptase (TERT)." (PMID 33247684, 2020). "Thyroid cancers with BRAF and TERT tend to have more aggressive phenotypes and often become resistant to traditional therapies." (PMID 31810221, 2019). "Interestingly, concomitant BRAF V600E were observed in our HVPTC patient with TERT promoter mutation who died of disease during follow-up, which was consistent with the previous reports that coexistence of BRAF V600E and TERT represented the more aggressive biological behavior in thyroid cancer." (PMID 28423545, 2017). "The results of this study reinforce the role of TERT upregulation together with other components of telomerase holoenzyme complex, such as TERC, as prognostic factors and preferential immortalization mechanism in thyroid cancer." (PMID 35979662, 2022). "Our results show that GABPA stable silencing does not universally reduce TERT transcription in TERT-mutant thyroid cancer cells and that it also controls TERT wildtype promoter (e.g., in Cal62 cells)." (PMID 35053525, 2022). "In this study, we comprehensively assessed the ability of the ETS family of transcription factors to control TERT transcription in thyroid cancer cells with and without TPMs." (PMID 35053525, 2022). "Apart from the well-established anti-senescence function of TERT, little is known regarding non-canonical effects on cellular function in thyroid cancer." (PMID 34676499, 2021). "As shown inFigure 1(a), immunohistochemistry results demonstrated that the level of TERT in human thyroid cancer tissues was higher than that in normal tissues adjacent to the benign lesions." (PMID 34482792, 2021). "The effect size of TERT mutation was not affected by the RAI total dose, which is consistent with the results of a recent study showing that TERT-mutant thyroid cancer is related to poor RAI therapy responses." (PMID 33562809, 2021). "TERT TaqMan SNP genotyping assay validation on qPCR was assessed by analyzing DNA samples from three thyroid carcinoma cell lines to ensure there was no cross-reactivity and because these cell lines had approximately 50% of mutant allele frequency." (PMID 33776938, 2021). "Previous studies have shown TERT expression is undetectable in normal thyroid tissue, low to absent in benign tumors, and elevated in thyroid cancers." (PMID 32849278, 2020). "Nevertheless, our results show that expression of TERT mRNA is not exclusive for malignant thyroid tumours, in accordance with previous studies reporting TERT mRNA in FTAs, hyperplasia, goiter and Graves’ disease." (PMID 32659948, 2020). "In line with this, TERT expression and telomerase activity are detected in thyroid carcinoma, but not in normal thyrocytes or in benign thyroid tumors." (PMID 31200515, 2019).